MYC (MYC proto-oncogene, bHLH transcription factor)
Diseases named in the same sentence as MYC in open-access papers (continued):
Sharing a sentence is not in itself a finding about the gene and the disease.
colon carcinoma (continued). "The transcription factor SOX2 is involved together with c-MYC, KLF4 and OCT3/4 in the induction and maintenance of pluripotent stem cells and has been also associated the expression of both SOX2 and β-CATENIN with metastases and poor prognosis in colon cancer." (PMID 24946763, 2014). "MYC plays a critical role in colon carcinomas that arise from de-regulated Wnt/ß-catenin signaling." (PMID 21533051, 2011). "Indeed, HCT116 colon cancer cells have approximately three-fold higher levels of MYC transcript and two-fold higher levels of MYC protein when compared to levels detected in HEK293 kidney cells." (PMID 21533051, 2011). "Although delimiting the precise elements at the MYC promoter that control Wnt/ß-catenin-dependent activation of MYC expression in colon cancer cells is a daunting task, it will ultimately be required to understand the relationship between de-regulated Wnt signaling and colon cancer pathogenesis." (PMID 21533051, 2011). "A recent study in PDCD4 knock-down colon cancer cell lines demonstrated that E-Cadherin loss is a key event for activating the β-catenin/Tcf-dependent transcription, leading to subsequent over-expression of the invasion-promoter genes u-PAR and c-MYC." (PMID 20831814, 2010). "In agreement with our evidence of MYC induction in DBTRG-05 apoptotic cells, the over-expression of MYC was already described to sensitize colon cancer cells to CPT-induced apoptosis and to be necessary, in rat fibroblasts, for DNA damage-initiated apoptosis in the G2 phase of the cell cycle." (PMID 18694480, 2008). "It has been suggested that cytoplasmic localisation of c-MYC in colon cancer may be due to alterations in the C terminus of the protein, reducing the efficiency of nuclear targeting." (PMID 18493233, 2008). "Thus, knocking out the NKD1 gene in colon cancer cells exceptionally inhibited cell proliferation, and this inhibition could be eliminated by overexpression of MYC, indicating that NKD1 promotes cell proliferation through MYC." (PMID 40675969, 2025). "Therefore, having established that all the three ASO-like 10–23 variants can achieve potent and durable inhibition of constitutively expressed exogenous eGFP in HeLa cells, we further established their activities on endogenous c-MYC mRNA knockdown in colon cancer HCT116 cells." (PMID 40037707, 2025). "Furthermore, NKD1 notably increases MYC protein expression in colon cancer cells." (PMID 40675969, 2025). "Functionally, the PPARδ/NKD1/MYC signaling pathway increased colon cancer cells’ proliferation, migration and angiogenesis capabilities in vitro and in vivo, suggesting that NKD1 could serve as a potential therapeutic target for colon cancer diagnosis and treatment." (PMID 40675969, 2025). "Previous studies have confirmed that YAP1 may partially reverse the inhibitory effect of SNTB1 knockdown on the phenotype of CRC cells and the Wnt/β‐catenin/MYC signaling pathway, thereby affecting the invasiveness of colon cancer cells and the growth and metastasis of tumors in vivo." (PMID 41152153, 2025). "Furthermore, another study has reported that SULT2B1 is highly expressed in chemoresistance colon cancer and radio-resistance tissues, which promotes cell proliferation and chemoresistance in colon cancer through its involvement in oncogenic signaling involving the OLR1/c-MYC/SULT2B1 axis." (PMID 39280099, 2024). "The present study reveals the selective chemotherapeutic efficacy of THZ531 in MYC-high MB, thus further highlighting the importance to diversify the treatments on the basis of the genomic and molecular profiles of the tumour, as already in use for other cancer types (i.e. breast and colon cancers)." (PMID 37599362, 2023). "Furthermore, the colon cancer cells were infected with lentivirus to confirm that c-MYC could orchestrate SULT2B1 expression." (PMID 34921134, 2021). "Therefore, exogenously altering Lnc-EPIC1 expression was ineffective in MYC-KO colon cancer cells." (PMID 33170148, 2020).
colon carcinoma (continued). "A recent study has shown that deletion of a single enhancer in colon cancer cells can lead to changes in expression of hundreds of genes, most likely due to the fact that the direct target gene regulated by that enhancer is the MYC oncogene (Tak and Farnham, unpublished data)." (PMID 26719772, 2015). "Conditions used to transfect sponges and plasmid control in the MCF7 cancer cell line were applied to the three colon cancer cell lines: HCT-15 (2 copies of MYC), HT-29 (4 copies of MYC), and SW-620 (7 copies of MYC)." (PMID 40940795, 2025). "Strikingly, most of the Wnt genes upregulated by HMGA1 in our murine model are also upregulated in human colon cancer, including the WNT effectors, ASCL2, AXIN2, CTNNB1, MYC, EPHB2, CD44, and ETS2 and the WNT receptors, LGR5, LRP5, and LRP6." (PMID 39895630, 2025). "To explore the potential signaling axis (HGF/MET/MYC) between CAFs and CRC, we conducted further validation using colon cancer cell lines HCT-116 and COLO205." (PMID 41234356, 2025). "Another study implicated PDE4D in the suppression of the AKT-mechanistic target of rapamycin (mTOR)-MYC proto-oncogene, BHLH transcription factor (MYC) signaling pathway, reducing the malignant properties of colon cancer cells." (PMID 40961924, 2025). "Further studies revealed that in colon cancer cells, the MYC protein is degraded through the autophagy pathway and that NKD1 hampers this process by suppressing the interaction between the MYC and LC3B proteins." (PMID 40675969, 2025). "In colon cancer HCT116 cells, the downregulation of oncogenic c-MYC RNA resulted in cell cycle arrest, reduced proliferation, and increased apoptosis." (PMID 40037707, 2025). "To validate our data analysis results, we extracted total RNA from patient colon cancer tissue and corresponding normal colon epithelial tissue and measured the mRNA expression levels of TIMP1, VEGFA, MYC, MSLN, EPHA2, ABHD2, and CD24." (PMID 38773226, 2024). "We confirmed that ARNT2 protein and mRNA were repressed in other cell lines including the human retinal pigment epithelial cell line ARPE-19 and that human colon cancer cell line DLD1 that had elevated MYC." (PMID 39184078, 2024). "Through qRT-PCR testing, we observed that in colon cancer tissue, the mRNA expression levels of VEGFA (p < 0.05), TIMP1 (p < 0.0001), MYC (p < 0.0001), and EPHA2 (p < 0.05) were higher than in normal tissue." (PMID 38773226, 2024). "Its deletion downregulates k-RAS expression downstream of β-catenin and simultaneously inhibits colon cancer cell proliferation, whereas IGF2BP1 overexpression increases c-MYC and K-RAS expression and promotes colon cancer cell proliferation." (PMID 36844874, 2023). "For example, oncogenic MYC expression has been reported to be promoted by WNT signaling and AHCTF1 through SE-mediated gene gating and to increase the rate of colon cancer cell proliferation." (PMID 35186035, 2022). "We also examined the expression of genes and transcription factors in key metabolic signaling pathways across the subpopulation, the most abundant genes in colon cancer were PDK1, NRF1, MYC, and HIF1A." (PMID 35755820, 2022). "These DEGs, significantly altered in human colon cancer tissue (TCGA) (Supplemental S4), are ones with both emerging roles (SEC24D, ABCC3, ATGL2B, and PCK2) and established roles (MYC and MUC2) in colonic tumorigenesis." (PMID 34845203, 2021). "In order to further determine the relationship between OLR1 and c-MYC in colon cancer, the expression data of OLR1 and c-MYC in GSE10950, GSE41328, and GSE75970 were normalized, respectively." (PMID 34921134, 2021).
colon carcinoma (continued). "Another lncRNA from the same family, CCAT2, also increases c-Myc levels in colon cancer cells, but by recruiting the transcription factor TCF7L2 to the MYC gene promoter." (PMID 34440124, 2021). "As detected by MTS assay, colony formation assay, and RT-qPCR, the proliferation, colony formation, and Ki67 expression of LoVo colon cancer cells was apparently decreased by sh-OLR1 treatment, which was abrogated by further oe-c-MYC treatment." (PMID 34921134, 2021). "The OLR1 stably knockdown cell lines and control cell lines were constructed to explore the regulation of c-MYC expression by OLR1 in colon cancer cells and its effect on the function of colon cancer cells." (PMID 34921134, 2021). "Colon cancer tissues and LoVo cells were attained, where OLR1, c-MYC, and SULT2B1 expression was detected by immunohistochemistry, RT-qPCR, and western blot analysis." (PMID 34921134, 2021). "Specifically, c-MYC accelerated Trp uptake by upregulating Trp transporters SLC7A5 and SLC1A5 in colon cancer cells and tissues." (PMID 33916690, 2021). "MYC, LEF1, KLF4, SALL4, and IRF4 were the five important TFs involved in the regulation of the immune response in colon cancer." (PMID 34938284, 2021). "Therefore, we believed that SULT2B1 might be a key downstream gene of c-MYC in colon cancer." (PMID 34921134, 2021). "The expression of YTHDF1 was found to be induced by the oncogenic transcription factorc-MYC, and this axis c-MYC/YTHDF1 promotes colon cancer cell proliferation and induces the resistance against anticancer drugs." (PMID 32316617, 2020). "In colon cancer, TCF3 has been reported to induce MYC transcriptional activation, but we found that OCT4 has a greater role in MYC transcription than TCF3." (PMID 32409685, 2020). "We also checked the correlation between ETV5 and colon cancer cell proliferating markers (MK167, MYC, MYBL2) in order to assess the effect of ETV5 over cell proliferation." (PMID 33658938, 2020). "In primary human colon cancer cells, pri-Can-1/-2/-3, the MYC (c-MYC) protein immunoprecipitated with Lnc-EPIC1." (PMID 33170148, 2020). "Lnc-EPIC1 siRNA resulted in downregulation of MYC targets, including cyclin A, cyclin D and CDK9 in colon cancer cells." (PMID 33170148, 2020). "The expression of MYC, LEF1, PPARδ, and ACAD9 were closely correlated in a Western blot comparing colon cancer and normal adjacent benign tissue of human samples." (PMID 31623618, 2019). "Colon cancer is initiated by the inactivation of APC, which leads to the activation of the WNT pathway and the development of colon cancer in a MYC-dependent manner." (PMID 31623618, 2019). "MYC protein and mRNA expression level were significantly decreased in AXT-treated colon cancer cells." (PMID 31263239, 2019). "Immunohistochemical analysis of MYC, Cortactin, and ZEB1 also showed AXT suppresses metastasis of colon cancer cells into lung." (PMID 31263239, 2019). "In breast and colon cancers, binding of linc‐RoR to AUF1 inhibits binding of AUF1 to MYC mRNA and thereby increases MYC levels." (PMID 30451365, 2019). "Hypoxia alone or combined with hypoglycemia contributes to c-MYC proteasomal degradation in aggressive colon cancer HCT116 cells; in consequence, low c-MYC levels are found in xenograft tumor cells located away from blood vessels in hypoxic regions." (PMID 31600993, 2019). "MYC knockdown reduced LEF1 mRNA expression in DLD1 cells, thus indicating that LEF1 is transcriptionally regulated by MYC in colon cancer." (PMID 31623618, 2019). "Previous studies have shown that the colon cancer stem cells isolated from HCT116 cells express high levels of PROM1 (CD133), CD44, EPCAM, SOX2, c-MYC, and NANOG." (PMID 29507661, 2018).
colon carcinoma (continued). "In conjunction with our previous work, we have demonstrated that ML327 is a novel small molecule that both represses MYC transcription and transcriptionally activates CDH1 in both colon cancer cells and neuroblastomas." (PMID 29207623, 2017). "On the contrary, the PVT1 downregulation in the MYC-driven colon cancer cell line HCT116 reduced its tumorigenic potential, indicating a direct role of PVT1 in controlling MYC abundance." (PMID 29165379, 2017). "A moderate positive correlation of RBP4 was observed with VEGFA in the primary colon cancer (r = 0.605) and with VEGFA (r = 0.631) and MYC (r = 0.499) in liver metastases." (PMID 28689994, 2017). "For this purpose, HCT116 colon carcinoma cells, which express high levels of endogenous MYC, were depleted of POLRMT, MYC, or both POLRMT and MYC using shRNA." (PMID 27590350, 2016). "Conversely, transcriptional activation of oncogenic lncRNAs are directly mediated by MYC, such as CCAT-1 in colon cancer and H19 in gastric cancer." (PMID 27340923, 2016). "Three (MYC, CCND1 and CD44) of the six downstream targets were reported to be transcriptionally regulated by the Wnt signaling in the colon carcinoma cells from which the HCT 116 (the cell line we used in this study) was derived." (PMID 26057633, 2015). "In this study, we identified ABCB5 as a novel c-MYC target gene and examined the role of the c-MYC-ABCB5 axis in 5-FU resistance in human colon cancer cells." (PMID 25689483, 2015). "In the human colon cancer cell line HCT116, two HOT regions were found in the MYC and CCAT genes, respectively." (PMID 26113264, 2015). "Comparison with gene expression profiling shows that enhanced expression andfunction of the MYC oncoprotein, a downstream effector of both WNT- and RAS-dependent signaltransduction, is a common denominator of a vast majority of colon tumors." (PMID 25253726, 2014). "We therefore engineered a C-terminal MYC-tagged version of human FJX1 and expressed it in human embryonic kidney cells (HEK293T) and colon cancer cells (SW480, KM12C)." (PMID 23922772, 2013). "Starting from human colon cancer cells showing aberrant WNT/β-catenin/TCF signaling, hyperactivated MYC, and silenced BASP1, we generated stable cell lines overexpressing BASP1, either ectopically, or by reactivating the dormant BASP1 promoter using a lentiviral CRISPR-based system." (PMID 41785318, 2026). "Because MYC is a widely researched oncoprotein, we investigated whether NKD1 stimulates colon cancer progression through MYC." (PMID 40675969, 2025). "Studies have demonstrated that the c-MYC protein is degraded through the proteasome pathway in most tumor cells; however, its degradation pathway in colon cancer cells has not yet been reported." (PMID 40675969, 2025). "To date, studies have revealed that the degradation of the MYC protein occurs mainly through the proteasome ubiquitination pathway; however, the degradation mode of the MYC protein in colon cancer has not yet been reported." (PMID 40675969, 2025). "Furthermore, immunofluorescence experiments revealed an obvious interaction between MYC and LC3B in colon cancer cells." (PMID 40675969, 2025). "Many investigations have demonstrated that the MYC protein is degraded through the proteasome ubiquitination pathway; however, the degradation mode of the MYC protein in colon cancer cells has not yet been reported." (PMID 40675969, 2025). "In colon cancer area, astaxanthin suppresses the metastatic capacity of colon cancer cell line HCT116 in vitro, and CT26 cells injected in BALB/c nu/nu mice, by inhibiting the MYC-mediated down-regulation of microRNA (miR)-29a-3p and miR-200a." (PMID 39334719, 2024). "In support of these results, by using ultra-low attachment plates and a specific medium to enrich cancer stem cells, we grow 3D tumourspheres of colon cancer stem cells and find high mRNA levels of CBLL1, LGR5, and c-MYC compared to those levels in 2D monolayer cell cultures." (PMID 38339195, 2024).
colon carcinoma (continued). "Based on these findings, c-MYC and HIF-1α have been identified as potential therapeutic targets in colon cancer, which could theoretically lead to clinical trials targeting these factors to promote anti-tumor activity." (PMID 37450923, 2024). "Recent research suggests that CCAT1 promotes colon cancer cell growth by increasing expression of the oncoprotein c-MYC and the oncogenic mRNA tumor suppressor candidate 3 (TUSC3), the target of miR-181b-5p in CRC cells, thus increasing glucose metabolism to fuel colon cancer cell growth." (PMID 37568815, 2023). "Nevertheless, another study showed that colon cancer-specific SEs were associated with the MAPK signaling pathway, and the sensitivity to JQ1 was not related to c-MYC expression among 14 colon cancer cell lines." (PMID 35277481, 2022). "Additionally, TSL suppressed the proliferation of colon cancer cells via the downregulation of Wnt target genes, such as CCND1 (cyclin D1) and MYC (c-myc) and decreased the cell viability in the MTT assay." (PMID 35053565, 2022). "In colon cancer cell lines CT26 and HCT-116, AST treatment (50–100 μM; 24 h) transcriptionally repressed an oncogenic transcriptional factor, MYC, and thereby enhanced the expression of miR-29a-3p and miR-200a, which are known to exhibit an anti-metastatic effect." (PMID 36555112, 2022). "It is reported that cordycepin could down-regulate c-MYC mRNA expression and induce Bax-dependent and death receptor 3 (DR3) pathway-mediated apoptosis in colon cancer cells." (PMID 35120580, 2022). "In line with this notion, we found that expression of the generic proliferation marker MKI67, WNT- and MYC-target genes, and the KEGG pathway ‘cell-cycle’ are expressed at significantly lower levels in CMS4 than in any of the other subtypes in primary colon cancer." (PMID 36147916, 2022). "In conclusion, high expression of c-MYC in colon cancer tissues and cells was observed, and knockdown of OLR1 could downregulate c-MYC and repress the proliferation and chemoresistance of colon cancer cells." (PMID 34921134, 2021). "In order to further explore whether OLR1/c-MYC/SULT2B1 axis could also modulate the growth and chemoresistance of colon cancer cells in vivo, a subcutaneous tumor transplantation experiment was implemented in nude mice." (PMID 34921134, 2021). "In short, knockdown of c-MYC could decline SULT2B1 expression to curtailed glycolytic metabolism, thereby inhibiting the proliferation and chemoresistance of colon cancer cells." (PMID 34921134, 2021). "The levels of OLR1, c-MYC, and SULT2B1 were upregulated in colon cancer tissues and cells." (PMID 34921134, 2021). "In colon cancer cells, circCTIC1 RNA binds BPTF and attracts it to the MYC gene promoter." (PMID 34440124, 2021). "As reflected by RT-qPCR, increased c-MYC and SULT2B1 expression in LoVo colon cancer cells was noticed following c-MYC overexpression, which was opposite after silencing c-MYC, indicating that c-MYC could upregulate SULT2B1." (PMID 34921134, 2021). "Moreover, knockdown of OLR1, c-MYC, or SULT2B1 weakened glycolytic metabolism, proliferation, and chemoresistance of colon cancer cells." (PMID 34921134, 2021). "From RT-qPCR result, OLR1 and c-MYC mRNA expression was obviously diminished in OLR1-silenced colon cancer cells, while in the presence of sh-OLR1, elevated c-MYC mRNA expression was observed in colon cancer cells after further oe-c-MYC treatment." (PMID 34921134, 2021). "Quantification of c-MYC (oncogene) and APC (tumor suppressor) mRNA levels help elucidate how the A. mexicana root methanol extract may be affecting colon cancer cells." (PMID 33826680, 2021). "MYC target proteins, including cyclin A, cyclin D and CDK9, were downregulated with Lnc-EPIC1 silencing, but upregulated after Lnc-EPIC1 overexpression in colon cancer cells." (PMID 33170148, 2020). "Further Lnc-EPIC1 silencing or overexpression failed to alter functions of MYC-knockout colon cancer cells." (PMID 33170148, 2020).